MT1JP (metallothionein 1J, pseudogene)
Synonyms: MTB; formerly MT1; MT1NP; MT1J
Gene: Transcribed unprocessed pseudogene on chromosome 16 (56,635,818 to 56,636,943, forward strand). Ensembl gene ENSG00000255986.
Diseases named in the same sentence as MT1JP in open-access papers:
MT1JP is named in the same sentence as 17 diseases in open-access papers, as found by Europe PMC text mining. Sharing a sentence is not in itself a finding about the gene and the disease. The quoted sentences say what the papers report.
gastric cancer (26 papers, 2018 to 2025). A primary or metastatic malignant neoplasm involving the stomach. "We aim to draw an objective conclusion of the association between MT1JP expression levels with OS for gastric cancer patients." (PMID 29794726, 2018). "For example, lncRNA MT1JP is associated with gastric cancer (GC) survival." (PMID 39210921, 2024). "Randomized controlled trials (RCTs), prospective cohort studies, and case–control studies will be used for the qualitative and quantitative synthesis of the meta-analysis to explore the association between MT1JP expression levels with OS for gastric cancer patients." (PMID 29794726, 2018). "Rescue experiments showed that downregulation of FBXW7 reversed MT1JP-induced inhibition of gastric cancer proliferation, invasion, and migration." (PMID 40534867, 2025). "Rescue experiments exhibited that downregulation of FBXW7 reversed MT1JP-induced inhibition of proliferation, invasion and migration in gastric cancer." (PMID 35928868, 2022). "In gastric cancer, lncRNA MT1JP binds miR-92a-3p to regulate FBXW7 expression, which in turn affects gastric cancer progression." (PMID 35646642, 2022). "In vitro experiment data showed that lncRNA MT1JP upregulation suppressed proliferation, invasion and migration and enhanced apoptosis of gastric cancer cells." (PMID 35928868, 2022). "LncRNA metallothionein 1 J, pseudogene (MT1JP) has been reported to be downregulated in cancers developed from liver, lung, colon and gastric cancer, suggesting its tumor suppressive role." (PMID 35703312, 2022). "The expression level of MT1JP was shown to be significantly lower in gastric cancer, hepatocellular carcinoma and lung cancer tissues (especially for lymph node metastasis and advanced-stage cancer) than that in adjacent normal tissues." (PMID 35270630, 2022). "On the other hand, LncRNA MT1JP expression is decreased in gastric cancer, and it inhibits the process of gastric cancer through competitively binding to miR-92a-3p and regulating the expression of FBXW7." (PMID 34789303, 2021). "The tumor-suppressing role of MT1JP has been reported in multiple cancer cells, including breast cancer, glioblastoma, bladder cancer and gastric cancer." (PMID 33557774, 2021). "In gastric cancer, lncRNA MT1JP as ceRNA sponges miR-92a-3p to regulate the expression of FBXW7 and then influence the progression of gastric cancer." (PMID 33968763, 2021). "For example, the lncRNA MT1JP regulates FBXW7 as a ceRNA by interacting with miR-92a-3p in gastric cancer." (PMID 33323548, 2020). "For instance, MT1JP functioned as a ceRNA to regulate FBXW7 in gastric cancer via sequestering miR-92a-3p." (PMID 32565736, 2020). "Both LncRNA BDNF-AS and MT1JP have been reported decreased in quite a few cancers including gastric cancer, bladder cancer and lung cancer, suggesting their potential role as a rather broad and sensitive tumor suppresser." (PMID 32514246, 2020). "In gastric cancer, lncRNA MT1JP regulated the expression of FBXW7 through competitively binding with miR-92a-3p, and played a role in inhibiting cell proliferation, migration, invasion and promoting cell apoptosis." (PMID 32661236, 2020). "In terms of BC, one recent study presented the first evidence that MT1JP overexpression markedly inhibits invasion and enhances cisplatin sensitivity of BC cells, which is coincident with gastric cancer results." (PMID 31744046, 2019). "In line with the our results, a previous study applied an mRNA/lncRNA microarray in 76 pairs of tumor and normal tissue sample from live, colon, lung and gastric cancer, and revealed that lncRNA MT1JP had remarkably lower expression in all tumor samples." (PMID 29720189, 2018).
gastric cancer (continued). "MT1JP is down-regulated in gastric cancer tissues and may serve as a disease progression biomarker and a potential therapeutic strategy." (PMID 35346215, 2022). "lncRNA MT1JP functioned as a ceRNA to regulate miR-92a-3p/FBXW7 in gastric cancer." (PMID 35936736, 2022). "LncRNA MT1JP was downregulated in gastric cancer tissues compared with adjacent normal tissues." (PMID 35928868, 2022). "Gastric cancer patients had a better prognosis, who often have higher expression of MT1JP." (PMID 35928868, 2022). "MT1JP regulates gastric cancer progression by binding to miR-92a-3p competitively with FBXW7." (PMID 35430805, 2022). "For example, miR-92a-3p is sponged by MT1JP to regulate the progression of gastric cancer." (PMID 32351327, 2020). "Decreased MT1JP expression is significantly associated with more lymphatic metastasis and advanced Tumor Node Metastasis (TNM) stage for gastric cancer patients, and in-vitro and in-vivo studies have shown the suppressive role of MT1JP on the migration and invasion of gastric cancer." (PMID 31744046, 2019). "Notably, low expression of MT1JP was related with poor prognosis in patients with gastric cancer." (PMID 35928868, 2022). "Mechanistic analysis showed that lncRNA MT1JP recruited miR-92a-3p and upregulated FBXW7 in gastric cancer." (PMID 40534867, 2025). "Mechanistical analysis demonstrated that lncRNA MT1JP sponged miR-92a-3p and upregulated FBXW7 in gastric cancer." (PMID 35928868, 2022). "Although expression of miR-92a-3p is elevated in gastric cancers, the ceRNA activity of lncRNA MT1JP can efficiently prevent miR-92a-3p repression of FBXW7 mRNA expression and induce apoptosis of gastric cancer cells." (PMID 35346215, 2022). "MT1JP regulated miR-214-3p/RUNX3 signaling pathway and subsequently inhibited proliferation and migration of gastric cancer." (PMID 35928868, 2022). "MT1JP, which severs as a ceRNA regulating FBXW7 expression, could influence the progression of gastric cancer." (PMID 34196116, 2021). "Subsequently, MT1JP was found as a ceRNA to bind to miR-214-3p to facilitate expression of runt related transcription factor 3 (RUNX3), and suppressed cell proliferation, invasion and migration in gastric cancer cells." (PMID 33557774, 2021). "Although several researches have investigated the association between development and metastasis of gastric cancer (GC) and the expression level of MT1JP, there are no consensuses about whether its expression is associated with overall survival (OS) and clinical feature for GC patients." (PMID 29794726, 2018).
breast carcinoma (6 papers, 2021 to 2022). "MT1JP was downregulated in breast cancer samples and its overexpression inhibited cell proliferation by downregulating miR-24-3p in breast cancer cells." (PMID 36613528, 2022). "MT1JP was also reported to inhibit biological activities of breast cancer cells in vitro and in vivo by regulating the miRNA-214/RUNX3 axis." (PMID 35703312, 2022). "MT1JP overexpression specifically sensitized breast cancer cells to cisplatin treatment by targeting miR-24-3p." (PMID 36613528, 2022). "In breast cancer cells, MT1JP repressed oncogenesis and reversed cisplatin resistance through sponging miR-24-3p and inhibiting the Wnt/β-catenin." (PMID 35928868, 2022). "In this study, overexpression of MT1JP in breast cancer cells significantly inhibited their proliferation and enhanced their cisplatin sensitivity, which seems to be discordant with our results." (PMID 33974236, 2021). "It has been reported that Lnc-408 upregulates LIMK1 signaling pathway via sponging miR-654-5p, thereby accelerating breast cancer metastasis and invasion, and Lnc-MT1JP has been proved to enhance the resistance of hepatocellular carcinoma cells to Lenvatinib via sponging miR-24-3p." (PMID 35012431, 2022). "Another recent study also showed that MT1JP was downregulated in breast cancer." (PMID 35703312, 2022). "MT1JP acts as a tumor suppressor by regulating miR-92-3p in breast cancer cells." (PMID 35703312, 2022). "Consistently, MT1JP exhibited tumor suppressive functions via sponging miR-92-3p and targeting miR-214/RUNX3 axis in breast cancer cells." (PMID 35928868, 2022).
lymph node metastasis (4 papers, 2018 to 2023). "Furthermore, our study found that expression of lncRNA MT1JP was prominently associated with lymph node metastasis and advance stage, suggesting a clinic pathological role of lncRNA MT1JP in GC." (PMID 29720189, 2018). "The MT1JP low expression is more common in patients with advanced stage or/and existence of lymph node metastasis." (PMID 33557774, 2021). "LncRNA MT1JP was significantly lower in GC tissues than adjacent normal tissues, and higher MT1JP was remarkably related to lymph node metastasis and advance stage." (PMID 29720189, 2018). "The expression level of MT1JP was significantly related with TNM stage and lymph node metastasis." (PMID 33557774, 2021).
bladder cancer (3 papers, 2020 to 2021). "MT1JP has previously been reported to act as a tumor suppressor in breast and bladder cancer and it has been reported that MT1JP may inhibit the proliferation, invasion and migration of tumor cells." (PMID 33974236, 2021).
lung carcinoma (3 papers, 2020 to 2022). "LncRNAs such as lnc ADAMTS9-AS2, MT1JP, and GAS5 act as tumor suppressors in lung cancer through lncRNA/miRNA ceRNA networks, which regulate the expressions of well-known tumor suppressors such as PTEN and TIMP2." (PMID 33412752, 2020). "In addition, lncRNAs such as MT1JP, MAGI2-AS3, PLAC2, TINCR, LINC00641, FENDRR (FOXF1 adjacent non-coding developmental regulatory RNA), TRHDE-AS1, and lncRNA-p21 act as tumor suppressors in lung cancer by sponging miRNAs." (PMID 33412752, 2020).
cholangiocarcinoma (2 papers, 2021 to 2024). A carcinoma that arises from the intrahepatic biliary tree (intrahepatic cholangiocarcinoma) or from the junction, or adjacent to the junction, of the right and left hepatic ducts (hilar cholangiocarcinoma). "LncRNA MT1JP is downregulated in cholangiocarcinoma tissues, and its expression is associated with TNM staging and lymph node metastasis." (PMID 38637832, 2024). "Gain- and loss-of-function experiments demonstrated that MT1JP inhibited cell proliferation, cell cycle transition, migration and invasion, and promoted apoptosis in cholangiocarcinoma cells." (PMID 33557774, 2021). "The present study aimed to verify the hypothesis and investigated the effect of MT1JP in cholangiocarcinoma cells via gain- and loss-of-function experiments." (PMID 33557774, 2021). "The TCGA database shows that MT1JP is downregulated in cholangiocarcinoma specimens, and its expression is positive correlated with that of fructose-1,6-bisphosphatase 1 (FBP1)." (PMID 33557774, 2021). "In order to investigate the roles of MT1JP in cholangiocarcinoma cells, MT1JP overexpresion plasmid was transfected into HCCC-9810 cells, and its siRNA was transfected into HUCCT1 cells." (PMID 33557774, 2021). "The results in this section demonstrated that MT1JP was downregulated and miR-18a-5p was upregulated in cholangiocarcinoma specimens." (PMID 33557774, 2021). "Subsequently, twelve paired of intrahepatic cholangiocarcinoma specimens were used for detection of MT1JP and miR-18a-5p expression levels by real-time PCR." (PMID 33557774, 2021). "MT1JP alleviated proliferation, migration and invasion, and induced apoptosis in cholangiocarcinoma cells by regulating miR-18a-5p/FBP1 axis." (PMID 33557774, 2021). "In this study, we found that MT1JP was downregulated in clinical cholangiocarcinoma specimens, and its expression was correlated with TNM stage and lymph node metastasis." (PMID 33557774, 2021). "In addition, GEPIA website showed that the expression level of MT1JP was positively correlated with that of FBP1 in cholangiocarcinoma tissues." (PMID 33557774, 2021). "CCK-8 assay showed that MT1JP inhibited cell viability in cholangiocarcinoma cells." (PMID 33557774, 2021). "In addition, miR-18a-5p was increased in cholangiocarcinoma tissues, which was negatively correlated with that of MT1JP." (PMID 33557774, 2021). "MT1JP was decreased and miR-18a-5p was increased in intrahepatic cholangiocarcinoma cells." (PMID 33557774, 2021). "According to TCGA database, MT1JP and FBP1 were downregulated and miR-18a-5p was upregulated in clinical cholangiocarcinoma tissues." (PMID 33557774, 2021). "The tumor-suppressing role of MT1JP has been verified in multiple cancer types, but its effect on cholangiocarcinoma has not been evaluated." (PMID 33557774, 2021). "Because MT1JP has previously been reported to act as a miRNA sponge, we hypothesized that MT1JP functioned by sponging miR-18a-5p and regulating FBP1 expression in cholangiocarcinoma." (PMID 33557774, 2021).
intrahepatic cholangiocarcinoma (2 papers, 2021 to 2024). A carcinoma that arises from the intrahepatic bile duct epithelium in any site of the intrahepatic biliary tree. "The expression of MT1JP in intrahepatic cholangiocarcinoma specimens and paired para-carcinoma tissues were detected by real-time PCR." (PMID 33557774, 2021). "In this study, we demonstrated that lncRNA MT1JP was downregulated in intrahepatic cholangiocarcinoma tissues." (PMID 33557774, 2021). "In this study, we analyzed the correlation between MT1JP expression and clinical characteristics of thirty intrahepatic cholangiocarcinoma patients, and found that the expression level of MT1JP was related with TNM stage and lymph node metastasis." (PMID 33557774, 2021). "The results in this section suggested that MT1JP retarded tumorigenesis of intrahepatic cholangiocarcinoma cells in nude mice." (PMID 33557774, 2021). "MT1JP was downregulated in intrahepatic cholangiocarcinoma specimens, and its expression was related with TNM stage and lymph node metastasis." (PMID 33557774, 2021). "MT1JP inhibited proliferation, migration, invasion and tumorigenesis and enhanced apoptosis in intrahepatic cholangiocarcinoma cells as a miRNA sponge to bind to miR-18a-5p to facilitate the expression of FBP1." (PMID 33557774, 2021). "MiR-18a-5p was increased in intrahepatic cholangiocarcinoma samples, and its expression was negatively correlated with that of MT1JP." (PMID 33557774, 2021). "Overexpression of MT1JP inhibited proliferation, cell cycle transition, migration and invasion, and induced apoptosis in intrahepatic cholangiocarcinoma cells." (PMID 33557774, 2021). "The results in this section suggested that MT1JP suppressed migration and invasion in intrahepatic cholangiocarcinoma cells." (PMID 33557774, 2021). "The results in this sections suggested that MT1JP inhibited proliferation and promoted apoptosis in intrahepatic cholangiocarcinoma cells." (PMID 33557774, 2021). "The overexpression plasmid and siRNA of MT1JP were transfected into intrahepatic cholangiocarcinoma cells to change the expression levels of MT1JP." (PMID 33557774, 2021). "As MT1JP was decreased in intrahepatic cholangiocarcinoma tissues, its expression was examined in several intrahepatic cholangiocarcinoma cell lines and normal primary intrahepatic cholangetic epithelial cells." (PMID 33557774, 2021). "Moreover, the expression of MT1JP was significantly decreased in intrahepatic cholangiocarcinoma samples." (PMID 33557774, 2021).
glioma (1 paper, 2021). A benign or malignant brain and spinal cord tumor that arises from glial cells (astrocytes, oligodendrocytes, ependymal cells). "In glioma and glioblastoma, MT1JP is downregulated in patient tissues and cell lines." (PMID 34947885, 2021).
hepatoblastoma (1 paper, 2022). Hepatoblastoma (HB) is a malignant hepatic tumor and is the most common pediatric liver cancer. "Moreover, metallothionein 1J pseudogene (MT1JP), despite playing an oncogenic role in tumors such as hepatoblastoma, colon, breast, prostate, and non-small cell lung cancers, functions as a tumor suppressor in RB." (PMID 35432447, 2022).
liver cancer (1 paper, 2023). An epithelial or non-epithelial malignant neoplasm that arises from the liver. "However, the selection of MT1JP as a biomarker in liver cancer is complicated by its apparent dual roles: in addition to being associated with lenvatinib resistance owing to its antiapoptotic ability, some studies have noted that MT1JP is actually a tumor suppressor." (PMID 36980210, 2023).
osteosarcoma (1 paper, 2025). A usually aggressive malignant bone-forming mesenchymal neoplasm, predominantly affecting adolescents and young adults. "Based on RT-qPCR results, plasma MT1JP levels were significantly lower in osteosarcoma patients than in controls." (PMID 39797974, 2025).
retinoblastoma (1 paper, 2020). A malignant tumor that originates in the nuclear layer of the retina. "Based on all eligible evidence, we found two lncRNAs:BDNF-AS and MT1JP as potential prognostic biomarker for retinoblastoma." (PMID 32514246, 2020). "LncRNAs PVT1, AFAP10AS1, HOTAIR, BANCR, H19, DANCR and LINC00202 were up-regulated in retinoblastoma tissues while MT1JP and BDNF-AS were down-regulated." (PMID 32514246, 2020). "LncRNA MT1JP and BDNF-AS were slightly decreased in retinoblastoma tissues, which was consistent with our analysis." (PMID 32514246, 2020).